TNF (tumor necrosis factor)
Diseases named in the same sentence as TNF in open-access papers (continued):
Sharing a sentence is not in itself a finding about the gene and the disease.
lung carcinoma (continued). "Furthermore, to determine agreement between the CRISPR-ELISA assay and conventional ELISA, we used the two platforms to analyze IL-8 and TNF-α in the plasma of 20 lung-cancer patients." (PMID 36498497, 2022). "Moreover, in early-stage human lung cancer, TANs promoted T cell cytotoxic function through the production of OX-40 ligand (OX-40L) and 4-1BBL (a member of the TNF) co-stimulatory molecules." (PMID 35406451, 2022). "In addition, by using NF-κB p65 transcription factor assay, we further found that TBrC, T (50 μg/mL) and a positive control Bay (0.62 μg/mL) also inhibited TNFα-induced nuclear transcriptional activation of NF-κB p65 in human lung cancer A549 cells." (PMID 35706933, 2022). "Furthermore, overexpression of ZNF24 significantly inhibited, while knockdown significantly increased, the phosphorylation level of P65 and IκB in lung cancer cells in response to TNFα stimulation." (PMID 36457047, 2022). "Thus, reducing IL-1β expression and increasing TNF-α level demonstrated amplified cytotoxicity against lung cancer cell lines." (PMID 34883728, 2021). "Similar results have been observed in another BLCA study, but also in colon, prostate, pancreatic and lung cancers, and might be related to enhanced TNFα, which induces cell death and decreases viability." (PMID 34204827, 2021). "Using lung cancer models, others have shown that miR-21 alters the tumor microenvironment by increasing the secretion of the pro-inflammatory cytokines TNF- α and IL-6, through the activation of NF-κB, which decreases the number of CD8+ TIL and promotes the polarization of M2 macrophages." (PMID 33672628, 2021). "In lung cancer, TNF-α enhances TGF-β1-induced EMT and enhances TGF-β1-induced cell contraction." (PMID 35069596, 2021). "Prolonged sedentary behaviors are shown to increase the level of multiple inflammatory factors including tumor-necrosis factor-alpha, interleukin-6, and leptin that may contribute to the development of lung cancer." (PMID 34777480, 2021). "Indeed, TNF-α promoted adhesion of lung cancer cells to brain endothelium via a CD15s-CD62E manner, while blocking CD15s decreased this process." (PMID 34222020, 2021). "Here, we found that GABARAPL1—an autophagy-related gene—was increased in human NSCLC mesenchymal tumors compared to epithelial tumors, and induction of EMT in an A549 lung cancer cell line by TGF-β/TNF-α cytokines also led to an increase in GABARAPL1 expression." (PMID 34681055, 2021). "Indeed, in lung cancer, iron-loaded TAMs enhance the generation of ROS and pro-inflammatory cytokines (TNFα and IL-6), thus inducing tumor cell death." (PMID 33540645, 2021). "Previous studies have demonstrated that astragalin could increase the sensitivity of lung cancer cells to apoptosis by regulating caspase-dependent and NF-κB signaling pathways, and reducing TNF-α- or LPS-induced inflammatory NF-κB pathways activation." (PMID 33953676, 2021). "Furthermore, it induces the detachment and apoptosis of A549 human lung cancer cells, inhibits tumor cell growth in hepatocarcinoma, promotes TNF-α and IFN-γ expression, increases the Bax/Bcl-2 ratio, and activates caspases-3 to induce apoptosis." (PMID 33673020, 2021). "Also, it has been shown that high-density (40K) adipocyte-MSC increased the expression of interferon IFN-β, TRAIL, and tumor necrosis factor in H460 human lung cancer cells, significantly, induced apoptosis and suppressed the growth of human lung tumors." (PMID 35083017, 2021). "Lung cancer cells, however, often express phenotypes that resist the effect of TNF-α." (PMID 33262947, 2020). "Microorganisms can promote the occurrence of lung cancer through inflammation, immune responses, virulence factors, and metabolism; inflammatory factors, such as interleukin (IL), tumor necrosis factor (TNF)-α, and cyclooxygenase (COX)-2, are closely related to carcinogenesis." (PMID 33537234, 2020).
lung carcinoma (continued). "In another work, derivatives of UNA generated by reaction with oxalyl chloride and various phenyl amines inhibited tumor necrosis factor-α (TNF-α)-induced nuclear factor-kappa B (NF-κB) activation of H460 human lung cancer cells, with values of IC50 ranging from 0.94 to 15 μM." (PMID 33147723, 2020). "High expression of both USP4 and Twist1 was significantly associated with gene signatures of Notch and TNF signaling, suggesting that Twist1 may play a role in USP4-mediated lung cancer stemness." (PMID 32549341, 2020). "In the present study, our data support the notion that M-CSF secreted by Oct4-overexpressing lung cancer cells, which can be upregulated, in part, by TNF-α and IL-1β secreted from M1 macrophages, promotes Oct4-mediated M2 macrophage polarization and thereby increases tumor progression." (PMID 32487125, 2020). "Nonetheless, we could show that deletion of SRC-3 expression by CRISPR-Cas9 mediated gene editing significantly decreased both, basic and TNF-α induced IL-6 mRNA expression in our A549 lung cancer cell system." (PMID 32647362, 2020). "Furthermore, lung carcinogens are highly inflammatory and studies in Tunisia, for example, identified alterations in inflammatory genes- TNF-α, IL8, IL17A, IL17F, CCR2, and VDR Fok1 (rs2228570) and ApaI (rs7975232) that predispose to lung cancer." (PMID 33659210, 2020). "Our results showing upregulation of Oct4 in lung cancer cells either by coculture with macrophages or with TNF-α or IL-1β provide supports for the acquired cancer stem cell hypothesis." (PMID 32487125, 2020). "Our results show that tumor necrosis factor-α (TNF-α) and IL-1β upregulated Oct4 expression in lung cancer cells, which may in turn transcriptionally activated M-CSF expression." (PMID 32487125, 2020). "A study showed that JQ1 could disrupt the interactions between BRD4 and the acetylated lysine-310 residue on RelA, and inhibit the activation of TNF-α-mediated inflammatory cytokines in human lung cancer cells." (PMID 32303673, 2020). "Evidences indicate that increase of IL-6 was not only occurred in liver ablation, researches focus on lung cancer, including primary lung cancer and pulmonary metastases demonstrated that serum IL-8, IL-1β, IL-6, IL-10, IL-12 and TNF-α were significantly raised after radiofrequency thermal ablation." (PMID 32847533, 2020). "Since IL-6 and TNF-α can predict the occurrence and recurrence of hepatocellular carcinoma, TNF-α, IL-1, IL-6, and IL-8 might be used as biomarkers for prevention and prediction of lung cancer." (PMID 31832112, 2019). "Here, we chose to examine the effect that TNFα and IFNγ stimulation may exert on the immunopeptidome landscape of lung cancer cells." (PMID 30833945, 2019). "We found that in murine lung cancer model, ANF induced infiltration of CD8+ T lymphocytes into tumor tissues and increased IFNγ and TNFα expression, suppressed lung cancer cell proliferation, prolonged life-span of the mice, and significantly enhanced the therapeutic efficacy of anti-PD-L1 antibody." (PMID 30850589, 2019). "Since the inhibition of Ezh2 has recently been shown to amplify TNF-α–induced NF-κB signaling and inflammation in normal intestinal epithelium, it is plausible that our findings in lung cancer can be extended to other Kras-driven epithelial malignancies, such as pancreatic ductal carcinoma." (PMID 30487290, 2018). "TNF-α levels in the PBMCs could be further induced by low dose of LPS in all groups and although stimulation was stronger in both NSCLC and SCLC, overall TNF-α levels remained very low in the lung cancer groups." (PMID 30365491, 2018). "Together, our findings suggest that chemotherapy may activate immune response mechanisms such as IFNα, IFNγ, STAT3, and TNFα in lung cancer, which may generate a favorable tumor microenvironment for subsequent response to checkpoint immunotherapy." (PMID 29871672, 2018).
lung carcinoma (continued). "The expression of SLC2A5 is reported to be regulated by many factors such as substrate level, tumor hypoxia, oncogene, inflammatory factor TNF-α, and hormone levels (insulin, thyroxine, etc.)in other tumors, but its modulation in lung cancer remain unknown." (PMID 29531835, 2018). "By using recombinant cytokines, we also showed that TNF-α is a cytokine that may induce cytotoxicity in mouse lung carcinoma cells but only when combined with IFN-γ." (PMID 29276511, 2017). "Therefore, in this study, we investigated the effect of SAHA on HDAC activity and cell death, and suggested a promising combination strategy using TNF-α to improve anti-cancer effect of SAHA in lung cancer cells." (PMID 28099148, 2017). "Interestingly, we also observed that lung cancer cells promoted M2 polarization in macrophages as indicated by changes in levels of the M1-macrophage markers TNF-α and IL-12 and the M2-macrophage markers IL-10 and TGF-β." (PMID 29245941, 2017). "In this study, only TNF-α synergistically intensified cell death in SAHA-treated lung cancer cells." (PMID 28099148, 2017). "The low circulating levels of TNF-α in the bloodstream might have beneficial effects in lung cancer patients." (PMID 28101811, 2017). "We therefore propose a novel mechanism for TNF-α augmented lung cancer cell migration." (PMID 27556690, 2016). "We hypothesized that MUC1 activation in both lung cancer cells and TAMs may trigger TNF-α mediated signaling events that promote CSC generation." (PMID 27276704, 2016). "Moreover, the expression of this specific ST3GAL4 mRNA is increased by TNF treatment in both the human bronchial mucosa and in A549 lung cancer cell line, and is correlated with sLex and 6-sulfo-sLex over-expression on glycoproteins." (PMID 27916834, 2016). "ATM inhibition largely decrease TNF-α augmented lung cancer cell migration." (PMID 27556690, 2016). "Paclitaxel treatment increased TNFα secretion in lung cancer cells." (PMID 27737687, 2016). "In our observation, TNF-α level has a positive correlation with metastasis of lung cancer, indicating that tumor cells itself might regulate metastasis in autocrine manner." (PMID 27556690, 2016). "In addition, miR-224 attenuated TNF-α induced apoptosis by direct targeting of CASP3 resulting in reduction of cleaved PARP1 expression in lung cancer cells." (PMID 26307684, 2015). "In conclusion, SIRT1 could contribute to the development of lung cancer through TNF-α/β-catenin axis." (PMID 26318035, 2015). "While Erk1/2-NF-κB pathway was reported to be partially involved in inflammatory factors TGF-β1, TNF-α and IL-6 correlated lung cancer invasion, p38-NF-κB and STAT3-NF-κB pathways were demonstrated to inhibit miR-365 expression and regulate IL-6 repressing miR-98 levels respectively." (PMID 26528698, 2015). "Indeed, overexpression of claudin-1 was shown to induce EMT through activation of slug and zeb1 in human liver cells, and to mediate TNF-alpha induced cell migration in human lung carcinoma." (PMID 25171249, 2014). "Elevated levels of procoagulant factors, such as lupus anticoagulant, anticardiolipin antibodies to factor VIII, and certain cytokines such as interleukin-6 and tumor necrosis factor, have also been identified as increased risk factors for VTE in patients with lung cancer." (PMID 24574864, 2014). "Stimulation with GM-CSF enhanced expression of mRNA coding of TNF-α, IL-1, and IL-6 in AMs and monocytes from patients with lung cancer in a time-dependent manner and isolation of AMs from patients with lung cancer receiving GM-CSF therapy and cultured with LPS showed enhanced IL-6 secretion." (PMID 26316944, 2014). "However, altered cytotoxic activity in AMs and tumour-associated macrophages (TAMs) has been shown to be mediated via decreased secretion of cytokines (IL-1, IL-6, and TNF-α) in patients with lung cancer." (PMID 26316944, 2014). "BTC induced the resistance of human lung cancer cells to TNF-α/CHX-induced apoptosis." (PMID 24629040, 2014).
lung carcinoma (continued). "Based on the TNF-α-mediated genes that were dysregulated in lung tumors, we developed a prognostic gene signature that effectively predicted recurrence-free survival in lung cancer in two validation cohorts." (PMID 25548907, 2014). "These analyses further implied the possibility that a subset of TGF-β target genes could be regulated by miRNAs, shedding light on the complexity of molecular events elicited by TGF-β and TNF-α in lung cancer cells." (PMID 23437179, 2013). "However, only a low level (< 10%) of apoptosis was detected in lung cancer cells following TNF-α treatment at 48 h." (PMID 23339680, 2013). "Interestingly, levels of phosphorylated YAP were reduced in the same breast and lung cancer cells overexpressing RASSF1A or RASSF1C and in lung cancer cells overexpressing RASSF1C upon treatment with TNF-α." (PMID 24327924, 2013). "First we characterized the effect of TGF-β and/or TNF-α on EMT in A549 lung cancer cells." (PMID 23437179, 2013). "In the present study, TNFα strongly increased Claudin 1 expression in human lung cancer cells." (PMID 22675434, 2012). "Interestingly, receptor expression for IL-6 increased with time, while receptor expression for TNF-α and IL-1β decreased with time, in the case of lung cancer cells interacting with astrocytes." (PMID 23271367, 2012). "Through these experiments, we found that TNFα and TGFβ1 may have different roles in these human lung cancer cells." (PMID 22675434, 2012). "Although, exogenous expression of a dominant negative mutant form of IKKβ sensitized lung cancer cells to TNF by way of NF-κB inhibition, it was unknown whether this approach would similarly sensitize lung cancer cells to TRAIL." (PMID 20977779, 2010). "Bioinformatic analysis through KEGG pathway annotation demonstrated that differentially expressed genes were primarily enriched in the TNF‐related signaling cascade, indicating that circFUT8 may affect the signal transduction of lung cancer cells by regulating this pathway." (PMID 41328768, 2025). "In breast and lung cancer models, TNF-α has been shown to modulate a chronic inflammatory circuit (TNF-α → CXCL1/2 → MDSC recruitment → S100A8) that disrupts the TME and facilitates chemoresistance and metastasis; interruption at any point in this cascade may markedly reduce tumors’ aggressiveness." (PMID 40430573, 2025). "Moreover, we found that serum TNFα levels were positively correlated with the proportion of PU.1+CD56+ cells in patients with lung cancer, but not in healthy subjects, suggesting a potential link between PU.1- expressing NK cells and circulating TNFα in the context of lung cancer." (PMID 40895524, 2025). "In addition, IL-4Rα blockade in the presence of IFNγ + TNFα significantly enhanced the autologous T-cell mediated cancer cell killing as measured by Annexin V positivity of EpCAM-expressing lung cancer cells and promoted the cancer cell elimination induced by PD-1 blockade." (PMID 40091029, 2025). "TNF-α was positively associated with lung cancer, while IFN-γ exhibits negative association." (PMID 38813211, 2024). "Ten blood cytokine levels, including; granulocyte-macrophage colony-stimulating factor, TNF (alpha), and IFN (gamma), IL1, IL6, IL12, IL4, IL8, IL10, IL5, were compared between 296 European-Americans and 170 African-Americans to determine their associations with lung cancer." (PMID 36874133, 2023). "In the lung cancer cells (A549 and H1299), WA pre-treatment suppressed cell adhesion, migration, and invasion by downregulating the expression of tumor growth factor beta 1 (TGFβ1) and tumor necrosis factor α (TNFα) expression as well as epithelial-mesenchymal transition." (PMID 37377934, 2023). "During thoracoscopic lobectomies for lung cancer, nalbuphine treatment prior to the induction of anesthesia also provided a significant analgesic effect, reduced the incidence of adverse reactions, and alleviated postoperative inflammatory responses with a reduced serum level of TNF-α." (PMID 36765695, 2023).
lung carcinoma (continued). "Furthermore, the continuous wound infusion of local anesthetics significantly alleviated systemic inflammation with a reduced level of plasma TNF-α, decreased pain scores and opioid intake, and accelerated the recovery of respiratory function in patients of lung cancer resections." (PMID 36765695, 2023). "For example, alterations of the lung and gut microbiome were associated with increased levels of several inflammatory serum cytokines, including IL-6 and TNF-α, in preclinical models of lung cancer, which could in part be remedied by the administration of probiotics." (PMID 36387148, 2022). "In addition, TNF-α was proved to stimulate tumor growth and metastasis in lung cancer-bearing mice." (PMID 36140220, 2022). "In addition, studies have found that IL-1β promotes the invasion and metastasis of lung cancer A549 cell line, thereby promoting the progression and metastasis of cancer, and TNF-α could promote the metastasis of lung cancer by inducing EMT." (PMID 35449557, 2022). "Thus, TNF-α inhibitors may enhance chemotherapy effectiveness and disrupt the metastatic process in lung cancer." (PMID 36241629, 2022). "Possible explanations for the improved prognosis echo many of the same sentiments cited in lung cancer, namely the use of BMI for patient categorization and alterations of the tumor immune microenvironment, with obese patients exhibiting higher levels of IL-6 TNF-α and c-peptide." (PMID 35326592, 2022). "Researchers found that TNF played a key role in inducing resistance to epidermal growth factor receptor inhibition in lung cancer, and suggested that a concomitant inhibition of epidermal growth factor receptor and TNF maybe a potentially new treatment strategy for lung cancer patients." (PMID 34983358, 2022). "However, it has to be noted that not all PBMCs responded to S1P treatment in terms of TNF-α and IL-6 release: 85.2% (46 out of 54) of lung cancer patients responded to S1P treatment with the release of TNF-α (red slice), while 86.8% (46 out of 53) with IL-6 release (red slice)." (PMID 36010601, 2022). "Moreover, the anti-inflammatory effect of FEE by reducing the NF-κB, COX-2, and TNF-α immunoreactions in mice, with B(a)P- induced lung damage, could be considered in the prevention of inflammation induced cancer of the lung." (PMID 34943656, 2021). "Therefore, EGFR inhibition leads to an increase in TNF production that may trigger secondary lung cancer progression." (PMID 33917839, 2021). "Moreover, IL-6 and TNF-α could promote metastasis of lung cancer by inducing epithelial-mesenchymal transition in the animal experiment." (PMID 32595734, 2020). "Thus, the research on whether the NF-κB signaling pathway activated by TNF-α can induce lymphatic metastasis with NSCLC will play a positive role in the research on the metastasis mechanism of lung cancer." (PMID 33158173, 2020). "Additionally, the inhibition of MMP-3 or MMP-9 could achieve similar results in NCI-H446 and A549 cells, confirming the crucial role of MMPs in TNF-α promoting lung cancer cell migration." (PMID 27556690, 2016). "Astrocytes have been shown to produce a wide variety of cytokines and growth factors; among them, it was suggested that IL-6, TNF-α and IL-1β may contribute to the development of brain metastasis by lung cancer cells, and IL-6, TGF-β and IGF-1 by breast cancer cells." (PMID 23271367, 2012). "We studied pre-treatment and pre-cycle four plasma levels of VEGF, sVEGFR-2, IL-8, TNF-α, sICAM-1 and bFGF in an unselected cohort of patients from these trials to analyse the biological effects of thalidomide treatment, and to investigate their utility as biomarkers in lung cancer." (PMID 22353811, 2012).